OGA (O-GlcNAcase)
Description:
[Isoform 1]: Cleaves GlcNAc but not GalNAc from O-glycosylated proteins. Deglycosylates a large and diverse number of proteins, such as CRYAB, ELK1, GSDMD, LMNB1 and TAB1. Can use p-nitrophenyl-beta-GlcNAc and 4-methylumbelliferone-GlcNAc as substrates but not p-nitrophenyl-beta-GalNAc or p-nitrophenyl-alpha-GlcNAc (in vitro). Does not bind acetyl-CoA and does not have histone acetyltransferase activity. [Isoform 3]: Cleaves GlcNAc but not GalNAc from O-glycosylated proteins. Can use p-nitrophenyl-beta-GlcNAc as substrate but not p-nitrophenyl-beta-GalNAc or p-nitrophenyl-alpha-GlcNAc (in vitro), but has about six times lower specific activity than isoform 1.
Synonyms: NCOAT; MEA5; MGEA5
Tractability: Small molecule: a structure with a bound ligand is known; a high-quality ligand is known; it belongs to a druggable protein family. PROTAC: ubiquitination databases record sites on it; a small molecule that binds it is known.
Target class: Enzyme; Hydrolase
Chemical probes: JNJ-65355394 (high quality), TP-040 (high quality)
Gene: Protein-coding gene on chromosome 10 (101,784,443 to 101,818,620, reverse strand). Ensembl gene ENSG00000198408.
Subcellular location: Nucleus (Isoform 3); Cytoplasm (Isoform 1)
Subcellular location (Human Protein Atlas): Cytosol
Gene Ontology:
Molecular function: [protein]-3-O-(N-acetyl-D-glucosaminyl)-L-serine/L-threonine O-N-acetyl-alpha-D-glucosaminase activity; identical protein binding; hexosaminidase activity; hyalurononglucosaminidase activity; catalytic activity, acting on a protein
Biological process: N-acetylglucosamine metabolic process; protein deglycosylation; glycoprotein catabolic process; glycoprotein metabolic process; protein O-linked glycosylation
Cellular component: cytoplasm; cytosol; membrane; nucleus
Genetic constraint (gnomAD): Loss-of-function variants: 16 observed, 75.95 expected, observed/expected ratio (o/e) 0.21, 90% interval 0.14 to 0.32. The upper end of that interval is the gene's LOEUF score, 0.32, which puts it in group 1 of 6, group 1 being the genes least tolerant of losing a copy. Missense variants: 713 observed, 1,024.7 expected, observed/expected ratio (o/e) 0.7, 90% interval 0.65 to 0.74. Synonymous variants: 378 observed, 351.95 expected, observed/expected ratio (o/e) 1.07, 90% interval 0.99 to 1.17.
Homologues: Orthologues: chimpanzee OGA (99% identical), macaque OGA (99% identical), rabbit OGA (99% identical), pig OGA (99% identical), rat Oga (97% identical), mouse Oga (97% identical), guinea pig OGA (92% identical), tropical clawed frog oga (82% identical), zebrafish oga (77% identical), dog OGA (73% identical), Drosophila melanogaster Oga (39% identical), Caenorhabditis elegans oga-1 (28% identical).
Diseases named in the same sentence as OGA in open-access papers:
OGA is named in the same sentence as 125 diseases in open-access papers, as found by Europe PMC text mining. Sharing a sentence is not in itself a finding about the gene and the disease. The quoted sentences say what the papers report.
tauopathies (22 papers, 2012 to 2025). "In animal models of tauopathy, treatment with Thiamet G, an OGA inhibitor, reduced neuronal loss, prevented brain atrophy, and inhibited tau aggregation." (PMID 39909381, 2025). "Because this process modifies the key protein involved in tauopathies, and because OGA is located on chromosome 10q24.1 (a locus associated with late-onset AD), interest has grown in O-GlcNAcylation as a therapeutic target." (PMID 33796956, 2021). "Clarifying the underlying mechanism by which OGA inhibition leads to the reduction of pathological tau and identifying translatable measures to guide human dosing and efficacy determination would significantly facilitate the clinical development of OGA inhibitors for the treatment of tauopathies." (PMID 28521765, 2017). "OGA inhibitors were tested for their utility in treating tauopathies using animal models that express only 4R human tau isoforms." (PMID 39909381, 2025). "Preclinical data showing beneficial effects of OGA inhibition on memory performance in mouse models of tauopathy and AD has led to significant clinical interest in OGA inhibitors as a potential treatment for neurodegenerative disorders in patients." (PMID 41477167, 2025). "In mouse models of tauopathy, O-GlcNAcase inhibitors lead to increased O-GlcNAcylation and decreased filamentous aggregates of tau." (PMID 39909381, 2025). "MK-8719 and LY3372689 are potent O-GlcNAcase inhibitors with potential applications in treating tauopathies and Alzheimer’s disease." (PMID 41300284, 2025). "A novel, highly potent and selective OGA inhibitor, MK-8719, has been developed and showing promising results in in vitro and in vivo tauopathies model." (PMID 37305556, 2023). "These widely reproduced protective effects of OGA inhibition in tauopathy models, and more recently in amyloid and synuclein neurodegeneration models, have stimulated interest in the potential for OGA inhibition in other NDDs." (PMID 37918804, 2023). "OGA inhibition through chronic treatment with OGA inhibitors reduces tauopathy phenotypes in several mouse AD models." (PMID 33610549, 2021). "It has been reported that the modulation of O-GlcNAcylation levels by azaserine or glucosamine or by overexpression of OGT or OGA plays an important role in regulating the toxicity of mutant huntingtin in the cellular model of tauopathy and Drosophila." (PMID 33317171, 2020). "With regard to tau, multiple studies have reported that OGA inhibition leads to reduced tauopathy and cerebrospinal fluid tau in AD models." (PMID 31160541, 2019). "MK-8719, a selective and potent small molecule inhibitor of OGA has shown promising results in the treatment of tauopathy such as Progressive Supranuclear Palsy (PSP)." (PMID 30697194, 2018). "Taken together, these studies pave a path forward for further development of OGA inhibitors to treat tauopathy in humans." (PMID 28521765, 2017). "Ongoing clinical trials with OGA inhibitors will provide additional insight into the potential of this mechanism to reduce tauopathy." (PMID 28521765, 2017). "Several previous reports have suggested that OGA inhibition represents a promising treatment for neurodegenerative diseases characterized by tauopathy." (PMID 28521765, 2017). "A corollary of this notion is that an ideal treatment for tauopathy should lead to a reduction of all these features, and indeed OGA inhibition appears to fulfill this criterion." (PMID 28521765, 2017). "To further establish the mechanism of OGA inhibitors as a potential treatment for tauopathies and to develop transitional tools, we undertook a systematic assessment of the effects of the OGA inhibitor Thiamet G in rTg4510 mice." (PMID 28521765, 2017). "In a validated pre-clinical model of tauopathy, the designed OGA-inhibitor Thiamet-G increased the O-GlcNAc-ylation of many proteins rapidly (hours) and stably (months) in wild-type and transgenic mouse brain." (PMID 24376810, 2013).
tauopathies (continued). "Pharmacological OGA inhibition has already demonstrated therapeutic potential in different preclinical models, providing a strong rationale for the development of OGA inhibitors as disease‐modifying agents in tauopathies." (PMID 40437880, 2025). "Of note, Thiamet-G and its derivative MK-8719, two OGA inhibitors that can cross the blood-brain barrier in vivo, have been proven to be effective for the treatment of tauopathies." (PMID 40021952, 2025). "O-GlcNAcase inhibitors are currently in clinical trials for tauopathies, and therefore it will be important to know whether these drugs might affect α-synuclein functions and dysfunctions at synapses in order to ward off any undesirable effects." (PMID 37991902, 2024). "Despite the controversy surrounding its expression levels, OGA’s status as a potential tauopathy target became more convincing when studies revealed that the oral administration of an OGA inhibitor thiamet-G to Sprague Dawley rats effectively reduced their brain tau phosphorylation level in vivo." (PMID 38844706, 2024). "Hence, OGA inhibitors have been tested in several clinical trials to target tauopathy and early symptomatic AD, leading to a recent FDA approval of the OGA inhibitor MK-8719 as an orphan drug for tau-driven neurodegenerative disease." (PMID 38619103, 2024). "Recently, new molecules targeting OGA have been studying for the treatment of tauopathy." (PMID 30697194, 2018). "Alternatively, the reduced effect may be due to the fact that tauopathy is more advanced between 12 and 16 weeks of age and thus less amenable to OGA inhibitor treatment." (PMID 28521765, 2017). "Although there is a consensus that OGA inhibition reduces pathological tau, the mechanism by which OGA inhibitors achieve this effect is unclear, and this uncertainty has hindered the advancement of OGA inhibitors for the treatment of tauopathies." (PMID 28521765, 2017). "Clarifying the mechanism by which OGA inhibition reduces tau pathology and addressing these translational gaps will greatly facilitate further advancement of this target for the treatment of tauopathies." (PMID 28521765, 2017). "The designed OGA inhibitor denoted Thiamet-G was tested here for the first time independently in vivo, in acute and chronic studies in Tau.P301L mice as validated pre-clinical model for tauopathy." (PMID 24376810, 2013). "However, it has yet to be determined whether OGA inhibition is beneficial for the treatment of AD and other tauopathies." (PMID 40695677, 2025). "In addition, other emerging targets such as o-GlcNAcase and GSK-3β that associated with tauopathy remain to be explored in tauopathy models." (PMID 35082657, 2021). "Another OGA inhibitor, PUGNAc, reduced tau phosphorylation in PC12 cells overexpressing human tau, and Thiamet-G, OGA inhibitor, also considerably decreased tau aggregation and prevented neuronal cell loss in vivo in tauopathy JNPL3 mice and 3×Tg-AD mouse model." (PMID 33317171, 2020). "The possible dynamic interplay between protein O-GlcNAcylation and phosphorylation has led to the hypothesis that inhibition of the OGA enzyme would promote O-GlcNAcylation of tau, thereby attenuating tau hyperphosphorylation and providing therapeutic benefit for AD and other tauopathies." (PMID 28521765, 2017). "Initial studies indicated that this compound reduce tau phosphorylation at some phosphorylation sites that can be abnormally phosphorylated in AD, suggesting that OGA inhibition may offer a potential therapeutic approach for slowing tau-mediated neurodegeneration seen in AD and other tauopathies." (PMID 22536363, 2012). "These collective studies have provided strong preclinical support for OGA inhibition as a therapeutic strategy to alter disease progression in a range of NDD, with tauopathies and AD in particular being a major focus." (PMID 37918804, 2023).
tauopathies (continued). "The OGA inhibitor ASN120290, that has been recently assigned the Orphan Drug Designation for the treatment of progressive supranuclear palsy (PSP) by the Food and Drug Administration has granted to ASN120290 reduced neurofibrillary tangles in mouse model of tauopathy." (PMID 37305556, 2023).
diabetes (20 papers, 2010 to 2025). "This attachment is removed by the enzyme, O-GlcNAcase (Oga), whose namesake gene contains a diabetes susceptibility locus in humans." (PMID 36672613, 2022). "In agreement with this notion, several lines of evidence indicated that in patients with diabetes, increased O-GlcNAcylation associated with chronic hyperglycaemia was also associated with an increased expression of OGA." (PMID 31164864, 2019). "Among these, human O-GlcNAcase (hOGA) has been reported to be closely linked to several diseases such as Alzheimer's disease, diabetes, and cancer." (PMID 31403045, 2019). "These increases in O-GlcNAcylation levels are concomitant with changes in OGT/OGA activity, and, interestingly, diabetes is associated with a sarcomeric re-localization of OGT and OGA." (PMID 30420836, 2018). "We hypothesized that deletion of OGA may predispose these mice to diabetes by STZ treatment." (PMID 36387851, 2022). "Reducing this PTM within normal levels, through AAV-mediated OGA overexpression, normalized markers of adverse cardiac remodeling and diastolic dysfunction during diabetes." (PMID 40747493, 2025). "Alzheimer's disease, diabetes, and several types of cancers have been linked to abnormal levels or behavior of O-GlcNAc, OGT, and OGA." (PMID 30237786, 2018). "The authors also showed that diabetes affects the mitochondrial levels of OGA and OGT and their localization and activity." (PMID 30420836, 2018). "Disruptions in the cycling of O-GlcNAc mediated by O-GlcNAc transferase (OGT) and O-GlcNAcase (OGA), respectively, is a driving force for aberrant cell signaling in disease pathologies, such as diabetes, obesity, Alzheimer's disease, and cancer." (PMID 30237786, 2018). "AD is frequently associated with type 2 diabetes mellitus (T2DM) and decreased brain O-GlcNAc levels; Inhibition of O-GlcNAcase (OGA) has been shown to reduce tau aggregation and Aβ production." (PMID 38721528, 2024). "OGA hydrolyzes the N‐acetylglucosamine moiety from proteins to regulate O‐GlcNAcylation, which plays a critical role in various human diseases such as cancer, diabetes, and neurodegeneration as a post‐translational modification." (PMID 38664976, 2024). "Yet, our analysis of liver samples in Ts2 mice showed an opposite profile in terms of O-GlcNAcylated/phosphorylated ratio, as observed in diabetes, advising for a brain-specific targeting of OGA with the aim to directly subject the brain and avoid possible disturbances in other organs." (PMID 33258073, 2021). "For example, determine whether acute overexpression of O-GlcNAcase, which has been shown reverse some of the adverse effects of diabetes on cardiac function, would also reduce sarcolemmal FAT/CD36 levels thereby reverse the metabolic dysfunction." (PMID 21494549, 2011). "Differences in gene expression involved in O-GlcNAcylation and the HBP, including OGT, OGA, GFPT1, and GFPT2, have been detected between diabetic and nondiabetic individuals, which may provide candidate susceptibility genes and diagnostic value for diabetes." (PMID 36768465, 2023). "In the current model, deletion of OGA in β-cells led to glucose intolerance and insulin secretion deficits in older mice, though animals did not develop hyperglycemia or overt diabetes." (PMID 36387851, 2022). "Investigating the role of OGA and OGT in the presence of diabetes." (PMID 36353238, 2022). "Protein abundance of OGA and the OGT:OGA ratio was not altered by diabetes or at any age." (PMID 32153425, 2020).
Alzheimer disease (16 papers, 2011 to 2026). A progressive, neurodegenerative disease characterized by loss of function and death of nerve cells in several areas of the brain leading to loss of cognitive function such as memory and language. "In humans, OGA is encoded by the OGA gene on chromosome 10 (10q24.1–q24.3) and maps to a genetic loci involved in Alzheimer’s disease." (PMID 36104770, 2022). "In the present study, we demonstrate that Interferon Regulatory Factor-1 (IRF-1), which is deficient in the brain of individuals with Alzheimer’s disease (AD), negatively regulates the O-GlcNAcylation levels of GluN1 through transcriptional regulation of the human OGA gene." (PMID 41029886, 2025). "Since OGA inhibition is being considered for long-term AD treatment, we replicated OGA inhibition for 1 month in the 5XFAD Alzheimer’s disease mice which express high APP protein levels." (PMID 37469955, 2023). "A potent inhibitor of the O-GlcNAcase enzyme that removes the modification from proteins, Thiamet G (TG), has been proposed to have potential benefits in Alzheimer’s disease." (PMID 35248135, 2022). "While some OGA inhibitors are already in phase 1 clinical trials for the treatment of Alzheimer’s disease, OGT inhibitors still have a long way to go." (PMID 33669256, 2021). "Recently, it has been found that OGA inhibitors prompted autophagy in two mouse models of Alzheimer's disease (AD) as well as in primary neuron culture." (PMID 31827688, 2019). "The findings provide good support for OGA as a promising therapeutic target to alter disease progression in Alzheimer disease." (PMID 25344697, 2014). "Development of OGA inhibitors has progressed and recently published reports describe a new and highly specific inhibitor of OGA, which was used in the study of Alzheimer disease." (PMID 23554695, 2011). "Therefore, the elevation of O-GlcNAcylation with O-GlcNAcase inhibitors are proposed as a novel therapy for (Alzheimer’s disease) AD." (PMID 39450274, 2024). "Therefore, this study provides additional support to develop OGA inhibitors as a treatment for Alzheimer’s disease and other neurodegenerative tauopathies." (PMID 28521765, 2017). "In addition, OGA inhibitors have been important for defining the augmentation of O-GlcNAc as a promising disease-modifying approach to combat several neurodegenerative diseases including both Alzheimer’s disease and Parkinson’s disease." (PMID 37918804, 2023).